DLK1 (delta like non-canonical Notch ligand 1)
Diseases named in the same sentence as DLK1 in open-access papers (continued):
Sharing a sentence is not in itself a finding about the gene and the disease.
lung adenocarcinoma (2 papers, 2018). A carcinoma that arises from the lung and is characterized by the presence of malignant glandular epithelial cells. "This confirms that Snail mediates the repression of the imprinted Dlk1-Dio3 locus in murine lung adenocarcinomas." (PMID 30190790, 2018). "In the K mouse model of lung adenocarcinoma, the Dlk1-Dio3 locus, including the miRNA cluster and Rtl1, Meg3 and Dlk1, was found upregulated in lung tumors compared to normal lung tissue." (PMID 30190790, 2018). "This is intriguing, as in KP lung tumors, Snail inhibits Dlk1-Dio3 locus gene expression while we have previously demonstrated that it enhances malignant progression in the KP mouse model of lung adenocarcinoma." (PMID 30190790, 2018). "Moreover, DLK1 and MEG9 were significantly hypomethylated in patients with SCC (p<0.001 and p=0.01, respectively), while in lung adenocarcinoma, DLK1 was very similar to the control group (p=0.127)." (PMID 29435111, 2018).
metastatic cancers (2 papers, 2024 to 2025). A carcinoma which has spread from the original site of growth to another anatomic site. "In this work, we have identified DLK1 as a cancer cell surface antigen that can be successfully targeted with an ADC in pre-clinical models of refractory metastatic cancers, namely ACC and SCLC." (PMID 39416174, 2024). "As we found DLK1 to be expressed in a subset of metastatic cancers apart from ACC, we hypothesized that ADCT-701 would be highly effective against DLK1+ tumors with low or no ABCB1 expression such as SCLC." (PMID 39416174, 2024). "Therefore, in this work, we screened normal tissue and metastatic cancer datasets for expression of Notch ligands (DLL1, DLL3, DLK1, JAG1, JAG2) and uncovered DLK1 (delta-like non-canonical Notch ligand 1) as a candidate cell surface immunotherapy target protein." (PMID 39416174, 2024). "We screened normal tissue and metastatic cancer datasets for expression of Notch ligands (DLL1, DLL3, DLL4, DLK1, JAG1, JAG2) and uncovered DLK1 (delta-like non-canonical Notch ligand 1) as a candidate cell surface immunotherapy target protein." (PMID 40595495, 2025).
Myocardial fibrosis (2 papers, 2024). "We have shown that the deletion of delta-like 1 homolog (Dlk1) accelerates fibroblast–myofibroblast differentiation and that Dlk1-null mice have marked myocardial fibrosis." (PMID 38577624, 2024). "that Dlk1 inhibits myocardial fibrosis by its expression in cardiomyocytes and cardiac fibroblasts." (PMID 38328889, 2024).
pituitary tumour (2 papers, 2013 to 2024). "Transwell assays demonstrated that DLK1 and RCN1 promoted the invasion of pituitary tumour cells." (PMID 39548559, 2024). "Expression of Dlk1 is also increased in human hormone-secreting pituitary tumours 27, whereas silencing of the Dlk1/MEG3 imprinted locus is detected in nonfunctioning pituitary adenomas 28,29." (PMID 23279263, 2013).
Prader-Willi syndrome (2 papers, 2023 to 2025). "MKRN3 is at the boundary of the region of Prader-Willi syndrome (PWS), which is associated with CPP in about 4% of cases, whereas DLK1 is at the locus of Temple syndrome, a rare disorder characterized by CPP in 80% to 90% of cases." (PMID 39839367, 2025).
prostate carcinoma (2 papers, 2013 to 2020). A carcinoma that arises from epithelial cells of the prostate gland. "Six of fourteen studies reported statistically significant (P < 0.05) expression changes for DLK1, demonstrating lower expression of the gene in prostate cancer tissues relative to healthy control tissues in four studies and higher expression in two." (PMID 23890537, 2013). "Our results suggest an overall tendency towards disruption of methylation at imprinted loci in prostate cancer tissue, and our data provide the first suggestion of disrupted imprinting patterns in cancer for four imprinted genes (DLK1, PLAGL1, SLC22A18, and TP73)." (PMID 23890537, 2013). "For example, the transmembrane protein DLK1 has been shown to negatively regulate NOTCH1, which is overexpressed in prostate cancer and is associated with human prostate cancer cell invasion; this suggests that DLK1 downregulation may promote cell invasion via increased NOTCH1 expression." (PMID 23890537, 2013).
sarcopenia (2 papers, 2018 to 2020). Progressive decline in muscle mass due to aging which results in decreased functional capacity of muscles. "We therefore hypothesized that a downregulation of the Dlk1-Dio3 locus may contribute to age-related muscle atrophy, providing a potential new mechanism for sarcopenia." (PMID 30505320, 2018).
steatosis (2 papers, 2019 to 2021). Increased lipid within the cytoplasm of cells. "Increased expression of DLK1 could act primarily on the growth hormone (GH) axis to shift the metabolic mode to fat acid oxidation, which has beneficial effects on hepatic lipid deposition and protects from steatosis." (PMID 31886292, 2019).
Truncal obesity (2 papers, 2020 to 2024). Obesity located preferentially in the trunk of the body as opposed to the extremities. "Additionally, patients with a congenital disease known as maternal uniparental disomy for chromosome 14, which causes overexpression of miR-379 of the Dlk1-Dio3 mat miRNA cluster, exhibit characteristic weight gain in early childhood that results in truncal obesity." (PMID 32106257, 2020).
adenoma (1 paper, 2013). A neoplasm arising from the epithelium. "Androgen receptor (AR) is expressed in 74 % of gonadotropinomas, and DLK1 is silenced in non-functioning adenomas, while it is highly expressed in functional adenomas." (PMID 23756599, 2013).
adipose tissue tumors (1 paper, 2013). "In liposarcomas (adipose tissue tumors) five out of nineteen tumors expressed Dlk1." (PMID 23577150, 2013).
alcohol abuse (1 paper, 2025). The use of alcoholic beverages to excess, either on individual occasions ("binge drinking") or as a regular practice. "Alcohol abuse can also alter methylation of the regulatory region of gene H19 and of genes DLK1 and GTL2 in the male gametes (40 men, alcohol consumers vs. controls)." (PMID 41153345, 2025).
alcoholism (1 paper, 2016). "miRNAs in Dlk1-Dio3 mat region had been identified as candidate for various diseases including cancer, psychiatric illnesses and alcoholism." (PMID 27135827, 2016).
Anorexia (1 paper, 2025). Lack of desire to eat (loss of appetite). "Supporting this, DLK1 levels decline during anorexia treatment, coinciding with reductions in BMAT and bone loss." (PMID 40852589, 2025). "This increase may be partially explained by elevated levels of DLK1 observed in women with anorexia." (PMID 40852589, 2025).
Atrophy (1 paper, 2020). Any weakening or degeneration, especially through lack of use. "Our results provide the first evidence of age‐dependent coexpression of the largest group of clustered miRNAs in the Dlk1‐Dio3 locus (at least 15 in mice and seven in humans) to inhibit a common atrophy‐related gene target, Atrogin‐1." (PMID 32495509, 2020).
biliary atresia (1 paper, 2022). A rare, biliary tract disease characterized by progressive obliterative cholangiopathy of the intra- and extrahepatic bile ducts, occurring in the embryonic/ perinatal period, leading to severe and persistent neonatal jaundice and acholic stool. "The authors concluded that DLK1 could be implicated in the activation of HSCs and in the fibrogenesis associated with biliary atresia." (PMID 35805898, 2022). "They found that DLK1 was upregulated during the early phase of biliary atresia and that the DLK1 protein was mainly, but not solely, present in HSCs." (PMID 35805898, 2022).
breast tumor (1 paper, 2019). "Of the 201 downregulated genes, DLK1 exhibited a 128-fold downregulation in breast tumor tissues." (PMID 31182966, 2019).
Colon cancer (1 paper, 2023). "By targeting the pericyte antigen DLK1, αDC1 vaccination led to significant changes in colon cancer vascular density, marked overall by reduced pericyte (PDGFR-beta and DLK1) and endothelial cell (CD31 and VEGFR2) markers." (PMID 37849752, 2023). "In tandem with biased Type-I immunity, immune-based reactions against vascular target such as DLK1 likely help account for tumor regression and protection in our described colon cancer model." (PMID 37849752, 2023).
corticotroph adenoma (1 paper, 2020). "The DLK1 expression levels yielded an H-score of 256.3±11.6 in somatotroph adenomas, 124.7±7.3 in lactotroph adenomas, 79±4.7 in gonadotroph adenomas, and 83.1±7.9 in corticotroph adenomas (P<0.001)." (PMID 33472171, 2020). "Intriguingly, we revealed distinct groups as follows: 1) somatotroph adenoma: high POU1F1 and high DLK1; 2) lactotroph adenoma: high POU1F1 and low DLK1; 3) gonadotroph adenoma: high FSHB and low DLK1, followed by high GATA2 and low DLK1; and 4) corticotroph adenoma: high TBX19 and low DLK1." (PMID 33472171, 2020). "Based on the transcriptomic analysis of 172 PitNETs, we suggest a solution as follows: 1) somatotroph adenoma: high PIT1 and high DLK1; 2) lactotroph adenoma: high PIT1 and low DLK1; 3) gonadotroph adenoma: high FSHB and low PIT1/DLK1; and 4) corticotroph adenoma: high TBX19 and low PIT1/DLK1." (PMID 33472171, 2020).
diabetic kidney disease (1 paper, 2023). Progressive kidney disorder caused by vascular damage to the glomerular capillaries, in patients with diabetes mellitus. "Of note are the TYRO3 (tyrosine-protein kinase receptor), DLK1 (protein delta homologue 1) and CTSH (cathepsin H) proteins, which are significantly associated with diabetic kidney disease (DKD)." (PMID 36349687, 2023).
experimental autoimmune encephalomyelitis (1 paper, 2023). An autoimmune demyelinating disease of the central nervous system that is produced experimentally in animals by the injection of homogenized brain or spinal cord in Freund's adjuvant. "In addition, the upregulation of Dlk1-Dio3 miRNAs has also been implicated the pathogenesis of multiple sclerosis (MS) and experimental autoimmune encephalomyelitis (a rodent model of MS)." (PMID 38153351, 2023). "For example, the Dlk1-Dio3 miRNAs targeted the PI3K/Akt/mTOR signaling pathway, which has been associated with the pathogenesis of lupus nephritis and MS/experimental autoimmune encephalomyelitis." (PMID 38153351, 2023).
folate deficiency (1 paper, 2024). A nutritional condition produced by a deficiency of FOLIC ACID in the diet. "In the present study, male and female pups from groups with vitamin B12 deficiency either alone or in conjunction with folate deficiency or from excessive supplementation in the F1 generation showed an increase in Dlk1 expression in fetal tissues (namely, the liver and brain)." (PMID 39543691, 2024).
gonadotroph adenoma (1 paper, 2020). "Hypermethylation of IG-DMR at the DLK1/MEG3 locus is the reason for the loss of MEG3 that occurs only in gonadotroph adenomas, and no gene in the DLK1/MEG3 locus was significantly downregulated in somatotroph adenomas compared to other PitNETs." (PMID 33472171, 2020). "Traditionally, the DLK1/MEG3 locus plays a tumor suppressor role in human gonadotroph adenomas." (PMID 33472171, 2020).
hepatic cirrhosis (1 paper, 2022). "Overactivation of the PTTG1/DLK1 axis in human cirrhosis was further confirmed." (PMID 35050550, 2022). "PTTG1 and DLK1 transcription are increased in rats and patients with hepatic cirrhosis." (PMID 35050550, 2022).
hypothalamic hamartoma (1 paper, 2023). "CPP may incorporate genetic alterations, such as MKRN3, DLK1, and KISS1; mutations in the epigenetic factors that regulate the HPG axis, such as Lin28b and Let 7; syndromes; central lesions such as hypothalamic hamartoma; and others." (PMID 38021712, 2023). "CPP may occur as genetic alterations, such as MKRN3, DLK1, or KISS1;as a part of mutations in the epigenetic factors that regulate the HPG axis, such as Lin28b and let-7; or as a part of syndromes, central lesions such as hypothalamic hamartoma, and others." (PMID 38021712, 2023).
Intellectual disability (1 paper, 2024). "Common features of TS14 are observed in DLK1 whole deletions including short stature, small hands and feet, relative macrocephaly at birth, prominent forehead in infancy, hypotonia and CPP with motor development and intellectual disability." (PMID 38715103, 2024).
liposarcoma (1 paper, 2013). A usually painless malignant tumor that arises from adipose tissue. "In liposarcomas Dlk1 expression was paralleled by expression of other characteristic muscle markers." (PMID 23577150, 2013). "This suggested that Dlk1 expression in liposarcomas could be indicative of a myogenic capacity." (PMID 23577150, 2013). "However, the consistent finding of Dlk1 in combination with muscle markers even in the liposarcomas suggests that Dlk1 is a direct element of the RMS characteristic regardless of cellular origin." (PMID 23577150, 2013).
liver failure (1 paper, 2022). A liver disease characterized by the liver losing or has lost all of its function. "Potential pharmacological targets for the treatment of liver failure include miR-126a, and miR-126a-5p has promising potential to be developed as a new drug because it downregulates DLK1 and promotes CD4 T-cell differentiation toward Th1." (PMID 36555554, 2022).
lung squamous cell carcinoma (1 paper, 2019). "Our precious studies based on mRNA micro-array analysis revealed that Delta-like homolog 1 (DLK1) was up-regulated expressed in human lung squamous cell carcinoma (SCC/LUSC)." (PMID 31661545, 2019).
male infertility (1 paper, 2024). The inability of the male to effect fertilization of an ovum after a specified period of unprotected intercourse. "Three additional genes (PCSK4, AP3B1, and DLK1) were identified as novel relevant players in human male infertility using the gene-wise burden test approach (P < 5.56E−04)." (PMID 39678461, 2024).
muscle tumor (1 paper, 2013). "Here, we investigate the possible roles of Dlk1 in skeletal muscle tumor formation." (PMID 23577150, 2013).
myeloid malignancies (1 paper, 2021). "Thus, the downregulation of DLK1 expression in MDS and AML BMSC observed in our study could contribute to pro-inflammatory signature of niche cells in myeloid malignancies." (PMID 33723276, 2021).
neuronal tumor (1 paper, 2019). Neuronal brain tumors are an uncommon group of central nervous system tumors that arise from cells with neuronal differentiation. "Another important player in hypoxia-induced cancer stemness is the DLK1, which has been shown to be up-regulated after hypoxia induction in neuronal tumors." (PMID 31191243, 2019). "DLK1 expression is induced by hypoxia, via HIF-dependent mechanism, in neuronal tumor cells, and plays a crucial role in maintaining the tumorigenicity of the CSCs." (PMID 31191243, 2019). "DLK1 expression was shown to be induced by hypoxia, via the HIF-dependent mechanism, in neuronal tumor cells and plays a crucial role in maintaining the tumorigenicity of the CSCs." (PMID 31191243, 2019).
non-alcoholic steatohepatitis (1 paper, 2020). "miR-379 was selected from the putative Dlk1-Dio3 mat miRNA cluster because it exhibited the greatest expression difference between NAFLD and non-alcoholic steatohepatitis in our preliminary study." (PMID 32106257, 2020).
ovarian diseases (1 paper, 2026). "To further explore the clinical relevance of DLK1 and NOTCH3 expression alterations, we investigated their levels in ovarian diseases, specifically POI." (PMID 41243550, 2026).
Pancytopenia (1 paper, 2012). An abnormal reduction in numbers of all blood cell types (red blood cells, white blood cells, and platelets). "Eighteen patients had pancytopenia, with an average level of DLK1 expression at (0.7618±0.4337)." (PMID 23691477, 2012).
pituitary deficiencies (1 paper, 2013). "Further work using this conditional allele of Dlk1 could prove crucial for unravelling the mechanisms that lead to the primary causes of the pituitary deficiencies." (PMID 23279263, 2013).
placental insufficiency (1 paper, 2015). Failure of the placenta to deliver an adequate supply of nutrients and oxygen to the fetus. "Therefore, increased expression of Dlk1 in response to maternal salt and HF diets may contribute to aberrant placental structure and placental insufficiency." (PMID 25991721, 2015).
prediabetes (1 paper, 2022). "DLK1 levels were significantly lower in girls with prediabetes compared to normoglycemic girls (p=0.02)." (PMID 36568069, 2022).
primary ovarian insufficiency (1 paper, 2026). "We also detected the upregulation of DLK1 in granulosa cells from patients with primary ovarian insufficiency." (PMID 41243550, 2026).
prostate tumor (1 paper, 2013). "Evidence was provided to support a tendency towards reduced expression in prostate tumor tissue at DLK1, PLAGL1, SLC22A18, with less conclusive expression data for WT1 and TP73." (PMID 23890537, 2013).
pulmonary neuroendocrine neoplasms (1 paper, 2022). "DLK1 has been shown to be a direct inhibitor of NOTCH genes in vitro, with emerging evidence of upregulation in vivo in pulmonary neuroendocrine neoplasms." (PMID 35538551, 2022).
relapsing-remitting multiple sclerosis (1 paper, 2021). The most common clinical variant of multiple sclerosis, characterized by recurrent acute exacerbations of neurologic dysfunction followed by partial or complete recovery. "Furthermore, twenty-six Dlk1-Dio3 miRNAs were identified to be significantly upregulated in the male patients with relapsing-remitting multiple sclerosis (RRMS) compared to those of healthy controls." (PMID 34062726, 2021). "The increase of Dlk1-Dio3 miRNAs was observed in the PBMCs from male but not female patients with relapsing-remitting multiple sclerosis (RRMs)." (PMID 34062726, 2021).
seminoma (1 paper, 2018). A radiosensitive malignant germ cell tumor found in the testis (especially undescended), and extragonadal sites (anterior mediastinum and pineal gland). "Moreover, our findings confirmed a strong association between oligozoospermia and imprinting defects (herein, on H19/IGF2, MEG3/DLK1, and SNURF DMRs for oligozoospermic patients with or without seminoma)." (PMID 30340650, 2018).
serous ovarian carcinoma (1 paper, 2021). "DLK1, a non-canonical notch ligand, is highly expressed in High grade serous ovarian carcinoma and has been associated with poor overall survival and PFS30." (PMID 33911091, 2021).
skeletal muscle tumour (1 paper, 2013). "Together our results suggest that Dlk1 is a candidate marker for skeletal muscle tumors and might be involved directly in skeletal muscle tumor formation through a modulatory effect on the myogenic programme." (PMID 23577150, 2013).
somatotroph adenomas (1 paper, 2020). "Based on the DEGs of 172 PitNETs, DLK1 had the most obvious effect on distinguishing somatotroph adenomas from other subtype PitNETs with a high expression level over 27 times." (PMID 33472171, 2020). "In somatotroph adenomas from 31 transcriptome groups, patients with high DLK1 expression appeared to have higher preoperative serum GH levels than patients with low DLK1 expression (r=0.58, P<0.001)." (PMID 33472171, 2020). "The imprinting disorders of the 14q32.2 region in somatotroph adenomas compared with other subtypes were identified, and a high-resolution profile at 14q32.2 (chr14:100,487,787-101,563,452, including DLK1/MEG3 locus) is shown." (PMID 33472171, 2020). "At least, combining analogs of somatostatin and blockade of the DLK1/MEG3 locus could be an effective treatment strategy for somatotroph adenomas, especially for patients with overactivation of the DLK1/MEG3 locus and resistance to standard treatment." (PMID 33472171, 2020). "Combined with the clinical phenotype, DLK1 and MEG3 were identified as characteristic molecules in somatotroph adenomas." (PMID 33472171, 2020). "Here, we showed the critical role of the DLK1/MEG3 locus in the differentiation of PitNETs in patients depending on the level of PIT1 and suggested the DLK1/MEG3 locus as a potential therapeutic target for somatotroph adenoma patients." (PMID 33472171, 2020).